MLKL (mixed lineage kinase domain like pseudokinase)
Diseases named in the same sentence as MLKL in open-access papers (continued):
Sharing a sentence is not in itself a finding about the gene and the disease.
infection (continued). "Considering MLKL deficiency did not affect the accumulation of MAIT cells in the steady-state, we next considered a role for MLKL in the regulation of MAIT cell expansion and contraction during infection." (PMID 36774342, 2023). "Following infection, direct activation of RIPK3 mediates recruitment of FADD, RIPK1 and MLKL to drive both MLKL induced necroptosis and RIPK3/Caspase-8 mediated apoptosis." (PMID 36175538, 2023). "Using immunoblotting-based biochemical analyses, we observed IAV-induced PANoptosis in BMDMs at both 12 and 24 h post-infection, as indicated by activation of CASP1, gasdermin D (GSDMD) and GSDME, along with CASP8, CASP3, and CASP7, as well as MLKL." (PMID 38005819, 2023). "Subsequently, the phosphorylated RIPK1, RIPK3, and MLKL promoted the ROS accumulation of mitochondria and Ca2+ influx in RAW264.7 cells, further exacerbating cell necrosis and persistent infection." (PMID 37175724, 2023). "Interestingly, inhibition of apoptotic pathways appears to permit HSV-induced necroptosis in astrocytes that is independent of ZBP1, as treatment with a pan caspase or a caspase-8 inhibitor did not reduce levels of phosphorylated MLKL following infection in ZBP1-deficient cells." (PMID 35549723, 2022). "Infection with the bovine NCDV and human DS-1 RVA strains was shown to activate receptor-interacting protein kinase 1 (RIPK1), RIPK3, and mixed-lineage kinase domain-like protein (MLKL), the key necroptosis molecules in virus-infected cells." (PMID 34668777, 2022). "Influenza A virus (IVA) infection is sensed by ZBP1, which activates RIPK3 and triggers MLKL-mediated necroptosis and FADD-mediated apoptosis." (PMID 35203445, 2022). "WT and STING-/- mice were treated intraperitoneally with GW806742X (MLKL inhibitor) or DMSO 12 h and 1 h before infection." (PMID 34135886, 2021). "We found the expressions of mRNA expression of caspase-1, GSDMD, caspase-3, MLKL, RIPK3, NLRP3, IL-1β and IL-18 and of proteins cleaved caspase-1, GSDMD, cleaved caspase-3 and pMIKL in the macrophages of the three infection groups to be upregulated (P<0.05)." (PMID 34513732, 2021). "At 24 h post-infection time, the transcriptional gene expression levels of TNF-α and MLKL were significantly increased by 5.65 ± 0.24 and 1.90 ± 0.38 times (p<0.01; p<0.05), respectively." (PMID 33176697, 2020). "Infection of cells with mutant MCMV that lacks M36 and M45 led to caspase 8 and RIPK3/MLKL activation and severely reduced viral replication." (PMID 30050058, 2019). "We found that the phosphorylation of MLKL (p-MLKL) at Ser345 was markedly induced by IAV infection in mouse lungs on days 6 and 7 post-infection." (PMID 31440477, 2019). "TNFα induces pathology in IOE infection, and TNFα is a driver of necroptotic cell death, a form of programmed necrosis involving RIPK1, RIPK3, and the effector protein MLKL." (PMID 30080899, 2018). "In whole BM we found similar expression of RIPK3 and MLKL in WT and Ifnar1-/- mice during IOE infection." (PMID 30080899, 2018). "In contrast, viability upon MCMV‐M45mutRHIM infection was much higher in IFN‐treated Zbp1−/− primary MEFs, despite comparable expression of RIPK3 and MLKL." (PMID 28716805, 2017). "Of note, rVSV infection of B16-OVA cells with either a caspase-3 or MLKL knockout neither led to a markedly altered cellular morphology nor significantly delayed or promoted cytotoxicity." (PMID 40896365, 2025). "Interestingly, we did observe a higher expression of MLKL in OPTN ‒/‒ cells at 2 and 4 h post‐infection." (PMID 40490945, 2025). "Starting from day 28 post infection, we observed an increase in the MLKL protein level in Mlkl+/+ lung homogenates and not in Mlkl−/− mice, but we did not detect phosphorylation of MLKL." (PMID 40950000, 2025). "The results showed that caspase-3 in HMEC-1 cells was processed into its active form only during the late stages of infection, and no phosphorylated MLKL (a marker of necroptosis) or activated GSDMD (a marker of pyroptosis) was detected." (PMID 40607949, 2025).
infection (continued). "In contrast to infection with ΔospD3, infection with ΔospD3ΔospI did not increase the levels of phosphorylated MLKL, RIPK1, and RIPK3, and cytotoxicity." (PMID 40931196, 2025). "In contrast to infection with ΔospD3, infection with ΔospC1ΔospD3 did not increase the levels of phosphorylation of MLKL or cytotoxicity, whereas caspase-8 activity was elevated in cells infected with ΔospC1 or ΔospC1ΔospD3." (PMID 40931196, 2025). "In contrast to infection with ΔospD3, infection with ΔospC1ΔospD3ΔospI did not increase the levels of phosphorylated MLKL, RIPK1, and RIPK3, and cytotoxicity." (PMID 40931196, 2025). "Additionally, PRV-GXLB-2013 infection induced a highly significant upregulation in mRNA expressions of TNF-α, IL-1β, IL-6, NF-κB p65, RIP3, and MLKL (p < 0.01), alongside a pronounced downregulation of IκBα (p < 0.01), in both brain tissues and C8-D1A cells." (PMID 40732040, 2025). "Previously, we observed upregulation of MLKL during the early stages of infection, which was independent of phosphorylation of MLKL required for canonical role of MLKL in executing necroptosis." (PMID 40490945, 2025). "Besides MLKL, we identified several components of innate immune signaling pathways to be antagonized by IE1 during infection by using necroptosis-related profiling." (PMID 38400065, 2024). "With longer infection time, CSFV could obviously increase RIPK3 and ZBP1 mRNA levels in PBMCs compared with the control, whereas it suppressed MLKL mRNA levels at 60 h of infection." (PMID 38100396, 2024). "However, phosphorylated MLKL was markedly increased in N2aC24 cells, but barely detectable in N2aC24L1-3 cells, after IAV/WSN infection." (PMID 39194237, 2024). "At 24 h after PPV infection, ZBP1 expression was still significantly increased in 481PTCsripk3−/−, however, there was no measurable expression of p-MLKL throughout the entire infection process." (PMID 39614405, 2024). "Subsequently, it has been documented that upon infection of host cells with influenza A virus (IAV), ZBP1 recognizes the IAV genome and in turn activates host RIPK3 kinase, which induces cell death through the MLKL-driven necroptosis pathway." (PMID 38100396, 2024). "Western blot results revealed that the expression of ZBP1, p-RIPK3, and p-MLKL in PTCs cells infected with UV-inactivated PPV did not increase with prolonged infection time, unlike in cells infected with the non-irradiated virus." (PMID 39614405, 2024). "Here, we show that even though the human cell lines HT29 and STA-et2.1 can upregulate p-MLKL expression upon TBZ treatment, p-MLKL induction is not observed in these cells upon infection with the three reoviruses (wt-R124, T3DK and jin-1) tested." (PMID 36768641, 2023). "However, a recent study showed an independent role for MLKL in driving IAV-induced cell death and inflammasome activation, particularly early in the infection cycle, in the context of TLR priming." (PMID 38005819, 2023). "The significance of necroptosis as a host defence mechanism against infection has been primarily defined by studies investigating the role of RIPK3 rather than MLKL." (PMID 36792599, 2023). "On the other hand, Ripk3 mRNA (and not MLKL) is upregulated after certain infections (such as: Mycobacterium Tubercolosis and Clostridium difficile), independent of interferon signalling, via mechanisms that involve promoter demethylation." (PMID 36175538, 2023). "By day 6 after infection, ZBP1 and MLKL mRNA levels were upregulated ~50-fold in the brains." (PMID 35215199, 2022). "Mice lacking necroptosis components RIPK3 or MLKL survived similarly to WT mice during infection with B. thailandensis, suggesting necroptosis is not required to control B. thailandensis." (PMID 34154417, 2021).
infection (continued). "At 6 and 12 h post-infection, the mRNA expression levels of caspase-3, caspase-1, GSDMD, RIPK3, MLKL, NLRP3, IL-1β, and IL-18 were upregulated in RAW264.7 macrophages infected with either E. faecalis CA1, CA2, or OG1RF strains compared to the levels in the control group." (PMID 34513732, 2021). "Mice lacking caspase-8, RIPK3, and RIPK1 (apoptosis/necroptosis) survived infection similarly to mice lacking either RIPK3 or MLKL, suggesting pyroptosis primarily protects against B. thailandensis in pyroptosis-competent mice." (PMID 34154417, 2021). "Contradictorily, genetic deletion of MLKL in BMDMs does not alter cell death following PR8 infection." (PMID 32260457, 2020). "Infection of HFFF-TERTs with HCMV prior to TBZ stimulation resulted in induction of a form of cell death that was not completely inhibited by GSK′872, which is suggestive of an RIP3-independent but MLKL-dependent mechanism." (PMID 32690704, 2020). "Finally, infection with strain AD169 or two independent strain Merlin UL36 deletion mutants rescued MLKL, suggesting that pUL36 was necessary as well as sufficient for MLKL degradation." (PMID 32690704, 2020). "Finally, infection of HFFFs with HCMV strains Merlin and AD169 for 48 h prior to TBZ stimulation suggested that inhibition of MLKL-dependent necroptosis required functional pUL36." (PMID 32690704, 2020). "In contrast to infection with ΔospD3, infection with ΔospC1ΔospD3 did not lead to phosphorylation of MLKL or induction of rapid cell death, whereas caspase‐8 activity was elevated in cells infected with ΔospC1 or ΔospC1ΔospD3." (PMID 32657447, 2020). "In primary mAECs, ZBP1 could be induced by H1N1 24 h post-infection and H1N1 infection at MOI of 5 was enough for ZBP1 induction, which correlated with the IAV-induced p-MLKL at Ser345." (PMID 31440477, 2019). "Simultaneously, mucins secretion in MLKL−/− mice was not different from that in WT mice before and after infection." (PMID 29456533, 2018). "There was clear evidence of MLKL phosphorylation 72 h following dl922-947 infection in the presence of zVAD.fmk but not at 24 or 48 h, and the effect of zVAD.fmk was partially rescued by the RIPK3 inhibitor GSK2791840B." (PMID 29238045, 2017). "MCMV‐M45wt infection did not change MLKL electrophoretic mobility (Fig EV2B), which is in line with our earlier observation that this virus does not cause cell death." (PMID 28716805, 2017). "•RIP3 phosphorylation increases post-infection, but not MLKL phosphorylation." (PMID 41550884, 2026). "Localized delivery of RIPK1/RIPK3/MLKL pathway inhibitors may confine necroptosis suppression to the infection site, thereby reducing local inflammation without compromising systemic immune defenses." (PMID 41142308, 2025). "The early phase of HMGB1 release at 6 h post-infection, which is cell death-independent but MLKL dependent, promotes the late phase of HMGB1 release via the activation of RAGE, initiation of a second wave of RIPK1/RIPK3/MLKL phosphorylation and occurs with cell necroptosis." (PMID 37798799, 2023). "Importantly, infection with any of the three reoviruses did not markedly increase this basal p-MLKL level." (PMID 36768641, 2023). "In both cell lines, there is expression of RIPK3, and this expression is not decreased upon infection by the viruses, suggesting that RIPK3 is still present in infected cells and blockade of p-MLKL expression was not caused by downregulation of RIPK3 expression." (PMID 36768641, 2023). "Major necroptosis marker proteins (MLKL, RIP1 and RIP3) and their phosphorylated forms were analyzed in whole spleen cell lysate from mice infected with L. interrogans and L. biflexa by western blot at 24h and 72h post infection, in comparison with uninfected control." (PMID 35392072, 2022).
infection (continued). "Necroptosis, a cell death mechanism involving TNFα stimuli, appeared in both organotypic cultures, consistent with the uncontrolled expression of TNFα and high levels of MLKL mRNA we found over the 4 days of infection in both the lungs and brainstem, compared to non-infected cultures." (PMID 34608167, 2021). "In addition to the important infection-busting role of MLKL in neutrophils, non-hematopoietic MLKL is also important for protection against gut-borne infections." (PMID 34071602, 2021). "Interestingly, we found that viral titers at 12 and 24 hpi were both increased in PK-15 cells with RIPK3 or MLKL gene knockdown, independent of the multiplicity of infection (MOI) of PRV infection." (PMID 34149651, 2021). "Direct MLKL activation may also avoid the potential accumulation of RIPK3-driven oxidative stress upon stimulation of the necrosome as has been reported following TNFα/Smac mimetic treatment, pathogen infection or necrosome formation." (PMID 32826875, 2020). "Necroptosis: Uninfected HOS and A549 cells had very low phosphorylation of RIP3 and if anything there was a decrease in p-RIP3 overtime in HOS and A549 cells upon SFV4 infection and no increase in p-MLKL after SFV4 infection in either HOS or A549 compared to their control." (PMID 31969562, 2020). "The patients have survived into their 6th decade without suffering from recurrent infections, indicating that MLKL and necroptosis in humans may be dispensable for the anti-bacterial and anti-viral capacity of necroptosis." (PMID 32358523, 2020). "Interestingly, these experiments also revealed that infection with Chlamydia did not prevent RIPK3 or MLKL activation induced by TSZ in HT29 cells and rather enhanced resulting necrotic cell death." (PMID 30375511, 2019). "As expected, in mock-infection cells, no MLKL was pull down together with RIP1." (PMID 28591723, 2017). "In contrast, infection with pandemic Cal/09 IAV did not significantly induce MLKL phosphorylation." (PMID 29203926, 2017). "Initial infection with P2 protected WT and MLKL-deficient animals equally against SARS-CoV-2 re-challenge, including challenge with P21, indicating that adaptive immune responses to SARS-CoV-2 are sufficient to protect against re-infection even in the absence of MLKL." (PMID 38286985, 2024). "The loss of RIPK3 or MLKL had no impact on the expansion or attrition of LCMV specific T cells as evidenced by comparable kinetics in virus-specific CD8+ T cells that recognize GP33 and NP396 across both RIPK3 and MLKL-deficient mice compared to WT mice at 8- and 35-days post infection." (PMID 36792599, 2023). "Interestingly, the levels of the phosphorylated forms of RIPK1, RIPK3, and MLKL, the major signaling molecules in the RIPK1-dependent necroptosis pathway, were observed as early as 4 hpi and continuously increased to 20 hpi in response to infection with both RVA strains." (PMID 34668777, 2022). "Blockage of type I IFN signaling starting 2 h before infection with anti-IFNAR1 mAb prevented the upregulation of MLKL and STAT1, another ISG, seen in wild type macrophages, without affecting the basal level of MLKL and STAT1." (PMID 40950000, 2025). "We did not observe changes in MLKL expression in the presence or absence of OPTN at 6 h post‐infection, but there was upregulation of MLKL 24 h post‐infection in Optn ‒/‒ HCE cells." (PMID 40490945, 2025). "Further analysis revealed a slight increase in p-MLKL and the presence of mildly cleaved Gasdermin D (GSDMD) at a high MOI (multiplicity of infection), although these changes were not significant, and no cleaved form of Gasdermin E (GSDME) was observed." (PMID 40891826, 2025). "Consistent with the response induced by prolonged treatment with the PAMP mimetic, MIRAS cells also induced p-MLKL at 24 and 48 h of HSV-1 infection compared with the controls, but did not affect cellular viability at 48 h after infection." (PMID 38570685, 2024).
infection (continued). "Further, the upregulation of TRADD and MLKL alongside the downregulation of the necroptosis inhibitor STUB1 suggests the priming, but not complete activation, of necroptosis in our in vitro infection model." (PMID 37795301, 2023). "Surprisingly, treatment with NSA, an inhibitor of MLKL, significant reduced LS174T cell death following ΔsopB infection, however, had no obvious effect on SL1344 induced cell death." (PMID 31024858, 2019). "Infection with VV expressing a truncated E3L lacking this z-DNA binding domain led to increased ZBP1 expression and excessive Type I IFN-induced RIPK3/MLKL-dependent necroptosis." (PMID 30050058, 2019). "Furthermore, robust phosphorylation of the necroptotic molecules MLKL and RIPK3 did not occur in Aim2–/– pBMDMs upon MPXV infection." (PMID 41225161, 2025). "Regarding pyroptosis and necroptosis, Gsdmd–/– mice, Mlkl–/– mice as well as Gsdmd–/–Mlkl–/– mice cleared the infection with normal kinetics, showing that neither GSDMD-mediated pyroptosis nor MLKL-mediated necroptosis were essential for host defense against C. rodentium." (PMID 37080966, 2023). "Consistent with this, receptor-interacting kinase 3 (RIPK3), the kinase phosphorylating MLKL, was markedly phosphorylated in N2aC24 cells, but not in N2aC24L1-3 cells, after IAV/WSN infection, indicating that RIPK3 is activated in N2aC24 cells, but not in N2aC24L1-3 cells, after IAV/WSN infection." (PMID 39194237, 2024).
neurodegenerative disease (14 papers, 2020 to 2025). A disorder of the central nervous system characterized by gradual and progressive loss of neural tissue and neurologic function. "Both RIPK3 and its downstream target, MLKL, are key players in this machinery, which is a cornerstone of neurodegenerative diseases." (PMID 36242717, 2023). "Another MLKL LOF gene variant (p.Gln48Ter, rs763812068) was found to be >20 fold enriched in a cohort of Hong Kong Chinese patients suffering from the neurodegenerative disease Alzheimer's, relative to a large ancestry-matched population." (PMID 35166320, 2022). "Transgenic models and pharmacologic inhibition have demonstrate that RIPK1, RIPK3 and MLKL are involved in many neurodegenerative diseases." (PMID 34922574, 2021). "Regulated necrosis or necroptosis, mediated by receptor-interacting kinase 1 (RIPK1), RIPK3 and pseudokinase mixed lineage kinase domain-like protein (MLKL), contributes to the pathogenesis of inflammatory, infectious and degenerative diseases." (PMID 32123582, 2020). "Moreover, as MLKL-mediated necroptosis exacerbates multiple neurodegenerative diseases by triggering cell death and neuroinflammation, we evaluated the production of multiple serum cytokines using the ELISA method." (PMID 38041169, 2023). "It should be considered that MLKL deficiency offered less benefit in some animal models, suggesting that MLKL might not be an excellent target for the treatment of neurodegenerative diseases." (PMID 34922574, 2021).
bacterial infection (8 papers, 2015 to 2024). "We believe that this may be due to bacterial infection that activates pathways such as MLKL, which leads to necroptosis caused by mitochondrial dysfunction and promotes inflammatory response, and ultimately leads to damage to intestinal epithelial structure." (PMID 37745216, 2023). "In order to investigate the effect of necroptosis on bacterial infection, MLKL-mediated necroptosis in flounder cells (FG-9307) was inhibited by the MLKL specific inhibitor GW806742X or NSA." (PMID 38292869, 2024). "To further confirm the observed phenomenon in vitro, we examined the level of MLKL phosphorylation in cecum following bacterial infection for 2 days." (PMID 31024858, 2019). "Notably, while beneficial during bacterial infection, Ponatinib blocks upstream effectors of necroptosis required in the cell defence against viruses; thus, future studies should aim to use selective MLKL inhibitors to reduce cardiac injury driven by SARS-CoV-2." (PMID 37081485, 2023). "Bacterial infection increased the expression of RIPK1/3 and MLKL." (PMID 38292869, 2024). "In support of this theory, 7 of the 10 murine models of bacterial infection examined here led to poorer outcomes in mice lacking MLKL." (PMID 34071602, 2021).